HDAC1 (histone deacetylase 1)
Diseases named in the same sentence as HDAC1 in open-access papers (continued):
Sharing a sentence is not in itself a finding about the gene and the disease.
tumor (continued). "Finally, HDAC1 knockdown inhibited tumor growth in nude mice in vivo." (PMID 28624794, 2017). "Since tumor associated fibroblasts may become activated with increased chemotaxis and promote tumor progression, our data suggest that epithelial derived exosomal maspin may suppress tumor-induced reactive stroma, at least in part, by inhibiting HDAC1-dependent transcriptome." (PMID 28009978, 2017). "Thus, Hdac1 and Hdac2 have a pro-oncogenic role in the Eμ-myc dependent tumor progression." (PMID 27886239, 2016). "Hence, an effect on proliferation and apoptosis upon Hdac1 and Hdac2 ablation could likely explain the delayed tumor appearance in our transplantation experiment." (PMID 27886239, 2016). "Eμ-myc tumor development was significantly delayed in mice having a single allele of Hdac2 and no Hdac1 (Hdac1Δ/Δ; Hdac2Δ/+), while this was not the case in mice with a single allele of Hdac1 and no Hdac2 (Hdac1Δ/+; Hdac2Δ/Δ)." (PMID 27886239, 2016). "However, the mechanisms by which HDAC1 is effective in preventing tumor formation is still unclear." (PMID 27907135, 2016). "Therefore, we first investigated whether ablation of Hdac1 and Hdac2 in B cells also induces tumor development." (PMID 27886239, 2016). "Thus, additional studies, including examining histone methylation and acetylation at specific promoters, are required to determine whether CoREST1 functions together with or independently of LSD1 and/or HDAC1/2 in promoting tumor angiogenesis." (PMID 25793264, 2015). "HDAC1 and 2, Class I HDACs, not only deacetylate histone/non-histone proteins, but also inhibit gene expression and modify tumor suppressive proteins associated with tumor progression." (PMID 25333250, 2015). "Despite the limited number of patients examined in this study, the significant positive correlation we observed between MBP-1 and HDAC1 expression in ErbB2-negative IDC suggests that their concomitant high expression may have a stronger diagnostic and prognostic significance in this tumor subtype." (PMID 23421821, 2013). "In this study, we have suggested that the abrogation of aberrant expression of HDAC1 activated the caspase-independent autophagic cell death and arrested the G1/S cell cycle transition in human Hep3B cells, and consequently suppressed the tumor cell growth in the xenograft animal model." (PMID 22496786, 2012). "The overexpression of HDAC1, HDAC2, HDAC3, and HDAC6, together with aberrant DNA methylation, contributes to tumor suppressor gene silencing." (PMID 41562705, 2026). "Notably, depletion of HDAC1 protein or loss of its catalytic activity resulted in significant alterations of the immunophenotype of ALK+ tumor cells, including a higher number of TCRb expressing cells and consequently increased dissemination of tumor cells into distant organs." (PMID 40175628, 2025). "Chidamide inhibits the activity of HDAC3, HDAC1, HDAC3, and HDAC10 selectively, suppressing tumor cell proliferation and triggers tumor cell apoptosis effectively." (PMID 40963853, 2025). "The RCOR2/LSD1 sub-axis suppresses RNF43 transcription to activate Wnt/β-catenin signaling in tumor cells, whereas the RCOR2/HDAC1/2 sub-axis inhibits CIITA and MHC-II expression in tumor cells to block activation of CD4+ and CD8+ T cells." (PMID 40608411, 2025). "In conclusion, our study sheds light on the intricate roles of HDAC1 and HDAC2 as tumor suppressors in ALCL development and highlights the therapeutic potential of HDAC inhibitors, such as Entinostat, in this context." (PMID 40175628, 2025). "Therapeutically, HDAC1 and SIRT1 can be targeted using small-molecule inhibitors that disrupt their enzymatic activity, reversing the epigenetic repression of tumor-suppressive miRNAs, including the miR-449 family." (PMID 41425255, 2025). "MTA1 contributes to tumor angiogenesis by deacetylating HIF-1α and upregulating the production of histone deacetylase-1." (PMID 40660330, 2025).
tumor (continued). "This study provides compelling evidence that peritumoral EA significantly inhibits tumor growth in TNBC, primarily enhanced recruitment of CD8+ T cells and downregulated expression of HDAC1." (PMID 40475010, 2025). "HDAC1, 2, 3, and 6 were the most ubiquitously expressed, while other HDAC genes had a lower expression for most tumor types." (PMID 40284412, 2025). "Systemic administration of HDACi delayed or completely abrogated tumor development, whereas T cell-specific depletion of HDAC1 or HDAC2 or inactivation of the catalytic activity of HDAC1 significantly accelerated lymphomagenesis." (PMID 40175628, 2025). "Simultaneously, RCOR2 inhibited CIITA expression through HDAC1/2-mediated deacetylation of histone H4 at lysine 16, leading to MHC-II silencing in tumor cells and subsequent impairment of CD4+CD8+ T cell immunosurveillance, thereby promoting immune evasion." (PMID 40608411, 2025). "Collectively, these findings underscore the therapeutic relevance of targeting HDAC1 and SIRT1 to restore tumor-suppressive miRNA expression and enhance chemosensitivity, providing a mechanistic basis for overcoming resistance in TNBC and other malignancies." (PMID 41425255, 2025). "To further validate the effect of p-CSNK2A1 T360/S362 on tumor growth in ESCC, we measured expression and phosphorylation levels of CSNK2A1 and HDAC1 in tumor samples obtained from our PDX models by Western blotting." (PMID 38652547, 2024). "The tumour tissues were homogenized to extract protein, and 15a downregulated the expression of DNMT1 and HDAC1, increased the acetylation of H3, and upregulated the expression of the apoptosis-related protein caspase-3 and the cell cycle-related protein p27." (PMID 38490978, 2024). "Overexpression of HDACs, such as HDAC1 and HDAC2, results in the deacetylation of histones at tumor suppressor gene promoters, further repressing their expression and fostering tumor growth." (PMID 39596558, 2024). "We further assessed the mRNA expression of all Class I HDACs (HDAC1, 2, 3 and 8), as well as previously reported HDAC4 (a Class IIa HDAC) in tumor organoids using qRT-PCR." (PMID 39567475, 2024). "NGF‐NGFR communication inefficiency suppressed mitotic spindle formation via HDAC1 unclear trans‐localization‐inhibited PREX1 expression, thereby suppressing the proliferation of T cells that had infiltrated into the tumor tissues of HCC patients." (PMID 38204220, 2024). "With the exception of HDAC1, SIRT6, and SIRT7, most HDAC genes were down-regulated in various tumor types." (PMID 39512688, 2024). "Among these 10 genes HDAC1, CASP3, REST, HMG20B, FZD7,GNAI3, FZD1 and EPHB4 had elevated expression in tumor group compared to the normal group, while KCNJ9 and SCRT1 were decreased." (PMID 38629068, 2024). "The HDAC1 can improve HIF-1α activity, which can promote aerobic glycolysis in tumor cells by inhibiting acetylation or degradation of HIF-1α." (PMID 39876842, 2024). "On the other hand, experimental evidence currently suggests that HDAC1 and HDAC2 can bind to ΔNp63α, a prognostic marker for HNSCC, forming an active transcriptional repressor complex that promotes tumor progression." (PMID 38983924, 2024). "In our comprehensive analysis of HDACs in DLBCL patients using public databases, we found that the expression levels of HDAC1, HDAC2, HDAC3, HDAC6, HDAC7, HDAC8, and HDAC9 were higher in tumor tissues compared to normal control for the first time." (PMID 38168914, 2024). "Compared to the control group after 48 h of treatment with TGT, the expression of genes JUN, TYMS, HSP90AA1, HDAC1, CDK1, and ESR1 was downregulated, which showed inhibitory effect on tumor cell proliferation." (PMID 38297292, 2024). "RE1-Silencing Transcription Factor corepressor (CoREST) complexes, containing HDAC1 or HDAC2, impede the functionality of FOXP3+Tregs through deacetylation and augment the body’s anti-tumor capacity." (PMID 39144146, 2024).
tumor (continued). "The collective results suggested that the inhibitory effect of HR488B on HCT116 cells was significantly reduced upon HDAC1 knockdown, confirming that HR488B exerts its anti-tumor activity via inhibition of HDAC1." (PMID 38062013, 2023). "Our previous studies showed that HIPK2 binds, along with histone deacetylase 1 (HDAC1), to the HIF-1α gene promoter repressing the HIF-1-mediated transcription of many target genes including VEGF, therefore restraining tumor growth." (PMID 36900356, 2023). "Recently, CUDC-907 has been demonstrated to inhibit both HDAC1 and HDAC2 as well as PI3K, Akt and mTOR expression and this resulted in an inhibition of NB tumor growth in a 3D spheroid tumor model." (PMID 37679770, 2023). "CPT1 coimmunoprecipitates with histone deacetylase 1 (HDAC1) in the nuclear extracts from MCF-7 cells, promoting tumor cell proliferation." (PMID 37927468, 2023). "In GBC, HDAC1 was first shown to interact with the transcription factor TCF-12, driving GBC tumor invasion and leading to poor prognosis." (PMID 37760477, 2023). "Concerning the expression levels of the three class I enzymes, they were highest in the case of HDAC1, which showed a median H-score of 200 (range: 0–300), with diffuse staining of moderate-to-high intensity across different WHO subtypes and tumor stages." (PMID 36901692, 2023). "A preliminary study has shown that histone deacetylase 1 (HDAC1) and SP1 are activated in tissues from OS and promote tumor progression." (PMID 37240338, 2023). "Dual HDAC1/2 and PI3K/AKT pathway inhibition by fimepinostat led to robust tumor growth inhibition in both ARPC and NEPC models including cell line– and patient-derived xenografts." (PMID 37823778, 2023). "We note multiple network connections between BUB1 and HDAC1, as well as connections between BUB1 and each of CDK1 (cell-cycle transition regulator) and APC (a tumor-suppressor protein within the Wnt signaling pathway)." (PMID 38030619, 2023). "Taken together, our data supported the notion that HDAC1 inhibitor retards the initiation and development of CC via mediating the TPX2/Snail axis, highlighting the anti-tumor molecular network functioned in CC." (PMID 35395834, 2022). "HDAC1 and HDAC2 were relatively upregulated and HDAC11 was downregulated in LGG and GBM tumor tissues." (PMID 35359455, 2022). "Oral intake of apigenin at doses of 20 and 50 g/day over eight weeks resulted in a significant decrease in tumor development, HDAC activity, and HDAC1 and HDAC3 protein expression in PC-3 xenografts in athymic nude mice." (PMID 35327559, 2022). "Whereas HDAC1 and HDAC2 promote UC, HDAC5 is often downregulated and only weakly expressed in UC cell lines, suggesting a tumor-suppressive function." (PMID 35624179, 2022). "As the NANOG/HDAC1 axis has been implicated as a central channel in the development of resistance to CTL-based immunotherapies, we believe that HDAC1 inhibition may be an effective strategy to control ICB therapy–refractory tumor cells with elevated expression of NANOG." (PMID 35104240, 2022). "SPHK II localizes mainly into the nucleus to inhibit DNA synthesis and regulate HDAC1/2 activity; downregulation of SPHK II reduces inflammation, proliferation and migration of tumor cells." (PMID 36010601, 2022). "Besides use tumor-bearing nude mice to further verify whether its HDAC1 can inhibit tumor growth." (PMID 35359455, 2022). "HDAC1 and HDAC2 were relatively upregulated whereas HDAC11 was downregulated in LGG and GBM tumor tissues." (PMID 35359455, 2022). "Further, it was also shown that SREBP1 promoted tumor cell metastasis by inducing EMT, and its mechanism was to inhibit E-cadherin by forming coinhibitory complexes with HDAC1/2 and Snail, thereby regulating EMT." (PMID 36518326, 2022). "HDAC3: Compared to HDAC1 or 2, even far less is known about the expression of the third member of the class I HDACs namely HDAC3 and its role in tumor progression and aggressiveness in GC." (PMID 36358890, 2022).
tumor (continued). "The NANOG/HDAC1 axis controls T cell trafficking and resistance to CTL-mediated killing in multiple types of NANOGhi tumor cells." (PMID 35104240, 2022). "We included HAP1 wildtype cells, next to cell lines with partial of full inactivation of HDAC1/2/3 and cells pre-treated with MS-275 or JQ12 before addition of the tumor drugs." (PMID 35994477, 2022). "In the early stages of T-cell development, HDAC1 and HDAC2 were also considered to act as tumor suppression, as either deletion of the first one or monoallelic loss of the second one in the absence of HDAC1 resulted in spontaneous lymphomagenesis." (PMID 35887172, 2022). "Based on the collected data, we found that SNHG25 silence inhibited in vivo tumor growth, accompanied by reduced tumor volume and weight, but such phenomena were counteracted to varying degrees after synchronous overexpression of SNORA50C or HDAC1." (PMID 35821006, 2022). "Thus, CHI could be a promising drug for MM patients with high expression of HDAC1 in tumor cells." (PMID 34539893, 2021). "We performed immunofluorescence assay (IFA) with two MDV lymphoblastoid tumor cell lines, MSB-1 and MKT-1, using antibodies against Meq and HDAC1 or HDAC2." (PMID 33437016, 2021). "HBx was shown to interact with HDAC1 and HDAC2, and HBx-induced stabilization of hypoxia-inducible factor 1 alpha (HIF-1α), a key regulator in tumor growth, angiogenesis and metastasis of HCC, involved deacetylation by HDAC1." (PMID 34361112, 2021). "DNMT1 forms complexes with UHRF1 and HDAC1 proteins in tumor cells, reducing expression of tumor suppressor promoter genes (e.g., P16INK4A, P14ARF, and P21) and hence fostering tumor growth." (PMID 33941774, 2021). "Another study revealed opioids’ effect on the expression of histone deacetylase 1 (HDAC1) and inducing tumor necrosis in the rat; also, HDAC1 -located in the nucleus of Sertoli cells of the testis- is involved in the spermatogenesis pathway." (PMID 34400949, 2021). "Other HDACs, including HDAC1, HDAC7, and HDAC8 are likewise necessary for the survival of such tumor cells." (PMID 34685500, 2021). "For instance, ROS increases the expression of Snail, a methyl-CpG binding protein that recruits DNA methyltransferase 1 (DNMT1) and histone deacetylase 1 (HDAC1), and induces the hypermethylation of E-cadherin, a tumor suppressor gene." (PMID 34679688, 2021). "Using four genetically defined murine PDAC cells we analyzed how hydroxyurea and entinostat, a specific inhibitor of the class 1 HDACs HDAC1/HDAC2/HDAC3, affect this tumor type." (PMID 34685500, 2021). "Abnormal expression of HDAC1 leads to overexpression of HIF-1α and VEGF in tumours, which subsequently promotes angiogenesis." (PMID 34395273, 2021). "CRISPR/Cas9 class I HDAC knockout of individual HDACs such as HDAC1 and HDAC2 inhibited invasiveness, and blocked local tumor growth in xenograft mice." (PMID 34654445, 2021). "Based on these observations, we first sought to target HDAC1, hence the use CI994 (Tacedinaline), a selective inhibitor of HDAC1 with significant activity in a number of in vivo tumor models." (PMID 32500025, 2020). "Genes related to oxidative phosphorylation and those related with chemoresistance and poor prognosis such as HNRNPA0, HDAC1, LDHB, AREG, and PSCA were upregulated in subgroups of brain metastasis-derived tumor cells in chemotherapy treated patients." (PMID 33170151, 2020). "Expression of HDAC1 (p = 0.02), HDAC3 (p = 0.04), HDAC4 (p = 0.001), as well as HDAC8 (p < 0.001) was significantly higher in M3 tumours compared to D3 tumours." (PMID 33316946, 2020). "HDAC1 and HDAC2, which are class I HDACs, exhibit a wide range of expression in tumours and strong enzymatic activity for many histone substrates." (PMID 31993801, 2020).
tumor (continued). "Stabilization of HDAC1 via the TCL1-pAKT-CHFR axis is a key element for NANOG-mediated multi-resistance and the stem-like phenotype in immune-edited tumor cells." (PMID 32850856, 2020). "The shared molecular targets of HDAC inhibitors identified via this drug screening were HDAC1 and HDAC2, suggesting that one or both play roles in the growth of core-like tumor cells." (PMID 32938908, 2020). "The importance of HDAC1 and HDAC2 in tumor cell survival provides a good rational for treating CML cells with imatinib in combination with pan-HDACis." (PMID 32430012, 2020). "FK228, a specific HDAC1 and HDAC2 inhibitor, was shown to have anti‐tumour effects though inducing G1/S transition arrest in GBM in vitro and in vivo." (PMID 31993801, 2020). "In fact, a previous study reported that UHRF1 forms a complex with HDAC1 and binds to methylated promoters of tumor suppressor genes such as CDKN2A, suggesting that UHRF1 mediates the tumor suppressor repression in cooperation with HDAC1." (PMID 31782885, 2020). "Among them, HDAC1, a class I HDAC, plays an important role in regulating DNA damage signals to maintain genomic stability and enhance tumor malignancy in vivo." (PMID 32903420, 2020). "Collectively, these data support the assertion that miR-204-5p has key tumor suppressor functions in HNSCC that are largely determined by its ability to silence SUZ12, SNAI2, JAK2 and HDAC1, and thus inhibit clinically aggressive tumors." (PMID 31938073, 2020). "High expression of FMNL1, with the help of HDAC1, upregulates CXCR2 to trigger EMT process and to facilitate cell migration and tumor metastasis in ccRCC." (PMID 33324547, 2020). "The amount of these enzymes is also context-dependent, with expression levels changing with tumour stage (as previously referred for KMT1A and HDAC1, among others)." (PMID 32429269, 2020). "HDAC1 (p = 0.05), HDAC3 (p = 0.02), the second probe of HDAC5 (p = 0.04) and of HDAC7 (p = 0.03), and HDAC8 (p = 0.004), were increased in tumours with 8q gain, while HDAC11 was decreased (p = 0.002)." (PMID 33316946, 2020). "For the groups treated with FA/MoS2 + NIR, FA/MoS2/si(HDAC1+Kras) and FA/MoS2/si(HDAC1+Kras) (NIR), the final tumor volumes were 8, 6, and 3 times of that of the original tumor volume while the control group's was 20 times of the original tumor." (PMID 32038249, 2019). "HDAC1 was expressed in 169 of 179 analyzable HL in a mean 82% of HRSC and 172 out of 179 analyzable cases in a mean of 83% of tumor-infiltrating lymphocytes." (PMID 30096875, 2018). "In conclusion, we showed that Sox6 plays a tumour suppressor role in PC, inhibiting EMT and tumour metastasis by modulating Twist1 expression through the recruitment of HDAC1 to the promoter of the Twist1 gene." (PMID 29369542, 2018). "It has been demonstrated that histone deacetylase 1 (HDAC1) regulates proliferation and neural differentiation of embryonic stem cells, neural stem cells, tumor stem cells and MSCs." (PMID 30662396, 2018). "Two studies found a correlation between miRNA449 down-regulation and HDAC1/HDAC3 up-regulation; two HDAC family members important for tumor cell proliferation." (PMID 30223590, 2018). "HDAC1 and HDAC2, two components of the NURD complex, are highly expressed in tumor patients with bad prognosis." (PMID 30310855, 2018). "It was recently demonstrated that selectively inhibiting HDAC1 and HDAC2 chemically decreases the tumor growth of SHH-MB in a murine model by inhibiting the Hedgehog pathway (Hh), which is further linked to an increase in GLI1 acetylation." (PMID 29099739, 2017). "Further analysis showed that YY1 expression was positively correlated with HDAC1 in HCC cell lines and tumor tissues." (PMID 28489564, 2017).